MYD88 (MYD88 innate immune signal transduction adaptor)
Diseases named in the same sentence as MYD88 in open-access papers (continued):
Sharing a sentence is not in itself a finding about the gene and the disease.
tumor (continued). "It has been found that the MyD88-dependent pathway activates NF-κB conduction and induces PD-L1 transcription, assisting tumor cells to participate in immune escape." (PMID 38785969, 2024). "Overexpression of Myd88 has been found to accelerate tumor progression and is correlated with the poor clinical outcomes in various types of cancers, including HCC." (PMID 37968706, 2023). "HDACs are well described as negative regulators of histone acetylation and the crosstalk between HDACs and Myd88 signaling has also plays an important role in tumor progression." (PMID 37968706, 2023). "As a signal transduction hub, Myd88 participates in multipathway signal transduction and participates in tumor initiation and progression through multiple mechanisms." (PMID 37953776, 2023). "It is a potent TLR2 and TLR9 ligand and mediates anti-tumor immune responses in MyD88 dependent pathway." (PMID 37122749, 2023). "The genes positively associated with NLR (CD39 (ENTPD1), PTEN, MYD88, MMP9 and LDH) are involved in processes of immunosuppression, inflammation and tumor-promoting activity." (PMID 37684649, 2023). "Here we report a case of BPDCN with a novel AFF4::IRF1 fusion predicted to lead to a loss-of-function of the IRF1 tumor suppressor, somatic mutations of ASXL1, TET2, and MYD88, as well as multiple intrachromosomal deletions." (PMID 38203475, 2023). "The genes positively associated with NLR [CD39 (ENTPD1), PTEN, MYD88, MMP9 and LDH] have immunosuppression, inflammation and tumor-promoting activity." (PMID 37684649, 2023). "Among the TLRs and their downstream (MyD88/IKKβ) we studied here, all had pro-tumor inflammatory functions, because their knockout led to reduced tumor burden, reduced angiogenesis, and reduced cell proliferation." (PMID 37283745, 2023). "TLR/MyD88 signaling pathway plays a great role in maintaining intestinal microbiota homeostasis, participating in inflammatory responses, inducing tumor cell cycle arrest, and modulating the host immunity against colorectal cancer." (PMID 38110638, 2023). "To identify somatically acquired second hits leading to B-ALL development in Pax5+/−;Myd88+/− mice, we performed whole-genome sequencing of paired tumor and germline tail DNA samples from eight Pax5+/−;Myd88+/− tumors." (PMID 37620322, 2023). "We observed that Myd88 reversed the inhibitory effect of miR-525-5p on tumor cell growth by transfecting cells with miR-525-5p mimics alone or together with Myd88 overexpression vector." (PMID 37953776, 2023). "Together, these results indicate that Myd88 expression in T cells is critical for antigen-specific CD8+ T cell responses and effector responses, which likely influenced results from tumor studies performed in total Myd88−/− mice." (PMID 37244938, 2023). "PD-L1 is an immunosuppressive molecule produced in response to TLR-4/MyD88 signaling cascade, which favors immune escape in tumor cells; its blockade has a positive impact in decreasing PDAC growth when associated with LPS reduction." (PMID 36838231, 2023). "Pathogenic bacteria in the tumor can activate TLR4 of mesenchymal cells and the MYD88 pathway, releasing the inflammatory factor IL-23, which in turn activates IL-17A, IL-6, and IL-22 to promote the development of CRC." (PMID 35914737, 2023). "In untreated mice, we found moderately improved outcomes in both Itgax-Cre/Myd88fl/fl and Lyz2-Cre/Myd88fl/fl mice, implicating MyD88 as an immunosuppressive factor in both DCs and myeloid cells during tumor growth." (PMID 37244938, 2023). "DMBA3-4 tumor rejection persisted in Ifng–/– (IfngKO); Klrk1–/– (Klrk1KO); Sting–/– (StingKO); Ifnar1–/– (Ifnar1KO); Ticam1–/–,Myd88–/– (Ticam1KO Myd88KO); and Ncr1iCre,ROSADTR mice." (PMID 37843274, 2023). "MyD88 signaling pathway plays an essential role in GPNMB+MDSC‐mediated tumor immune escape during CAC development and is a promising focus for revealing the mechanisms of MDSC that facilitate immunosuppression and tumor progression." (PMID 38140790, 2023).
tumor (continued). "Together, these data implicate MyD88 signaling in myeloid cells as a critical source of immunosuppression that hinders adaptive immune tumor control following radiation therapy." (PMID 37244938, 2023). "To discover the function of MYD88 in various types of cancer, we compared the expression of MYD88 in tumor and non-tumor tissues." (PMID 37456890, 2023). "Together, this data help explain the observed tumor-mediated cardiac dysfunction that is likely related to an upregulation in cardiac inflammation (MyD88) and autophagy (beclin-1) leading to metabolic perturbations and atrophy (p-FOXO1)." (PMID 36531941, 2022). "Recent studies suggest that extracellular HSP90α induces MyD88-IRAK complex-associated IKKα/β-NF-κB/IRF3 and JAK2/TYK2-STAT-3 signaling pathways in macrophages to promote tumor M2 polarization." (PMID 36158677, 2022). "Significant increases in IFNG, IL‐18, IL‐1β, IL‐8, TNF‐α, TLR4, MyD88, and NF‐κB levels were found in the P. copri and tumour control groups." (PMID 35735103, 2022). "We have proven that MDSCs are generated and that they proliferate and migrate in response to these cytokines and chemokines; furthermore, MyD88 signaling is essential for inflammation and tumor cell secretion." (PMID 35089465, 2022). "In terms of mechanism, the deletion of MyD88 leads to the inactivation of the Wnt/β-catenin pathway in tumor cells." (PMID 35836256, 2022). "Even in athymic nude mice, injection of TLA can inhibit tumor growth through activating myeloid differentiation factor 88 (MyD88) signal in bone marrow macrophages and promoting the expression of interleukin-12 (IL-12) in serum." (PMID 36118042, 2022). "Contrary to expectations, Il6, a well-known marker for tumor progression, was expressed greater in the MyD88-/- group in the short-term experiment, in particular after LPS stimulation." (PMID 36224342, 2022). "Blocking the MyD88-independent TRIF pathway resulted in protection, while blocking the MyD88-dependent pathway unexpectedly exacerbated pancreatic inflammation and tumor progression." (PMID 35619702, 2022). "Mechanistically, the microbiome has been reported to affect tumor-specific CD8+ T cells via TLR4 or TLR9/MyD88 signaling and the IL-12 pathway." (PMID 36387171, 2022). "Tumor regression is dependent on the MyD88-dependent signaling pathway involved in the expression of MHC-I." (PMID 36389785, 2022). "Blocking MyD88 signaling through the transgenic method has succeeded in inhibiting tumor growth in lung and ovarian in mouse model because it contributes to MDSC suppression." (PMID 35089465, 2022). "In this sense, genotyping of ctDNA by CAPP-Seq allows the recovery of 100% of the tumor-confirmed actionable mutations of DLBCL, such as EZH2, MYD88, and CD79B." (PMID 36230571, 2022). "MyD88-positive OC cells are equated to OC stem cells due to their resistance to pro-apoptotic signals and their ability to create a pro-inflammatory tumor microenvironment." (PMID 36231099, 2022). "The resulting data indicated that TLR4, MyD88, NF‐κB p65, and Bcl‐2 protein levels were markedly increased and Bax levels reduced after P. copri treatment compared with the tumour control group." (PMID 35735103, 2022). "Conditional knockout of MyD88 in intestinal epithelial cells (IEC) reduced tumor formation in Apc mice, accompanied by decreased proliferation and increased apoptosis of tumor epithelial cells." (PMID 35836256, 2022). "As displayed by RT-qPCR and Western blot analysis, IL-1β treatment led to upregulation of lncRNA CHRF and Myd88 along with downregulation of miR-489 in tumor tissues." (PMID 35711847, 2022). "We also demonstrated that PAUF’s tumor migration-promoting effects are exclusively through the TLR4/MyD88/NF-κB pathway." (PMID 36232715, 2022). "It is derived from the regulation of other mechanisms (such as the TLR4/MyD88 pathway) to promote tumor bone and distal metastasis." (PMID 34799997, 2022).
tumor (continued). "To confirm if BCG-infected tumor cells depend on MyD88 in the macrophages to polarize an inflammatory profile, we performed in vitro co-culture using infected MB49 with BMDMs from C57BL/6 WT or MyD88−/− mice." (PMID 34341449, 2021). "The Myd88L252P tumor signature also strikingly confirms that lymphoplasmacytic differentiation is at the heart of MYD88 related B-cell transformation in mice, a feature shared with WM tumors with the MYD88L265P mutation." (PMID 34017329, 2021). "During chemotherapy or radiotherapy, DCs require signaling through TLR4 and its adaptor MyD88 for efficient processing and cross-presentation of antigens from dying tumor cells." (PMID 34660305, 2021). "recently showed that MYD88 tumors express high levels of PD-L1 and that anti-PD-1 therapies induce T-cell dependent senescence of tumor cells." (PMID 34017329, 2021). "Zhang et al21 and Diao et al32 found that HSP72 and MYD88 Toll‐like receptor signals play a role in tumour exosome‐mediated MDSCs proliferation and tumour progression." (PMID 33955151, 2021). "We also measured TLR4, MyD88, NF-κB p65, Wnt 1, and β-catenin mRNA and protein expression in the xenograft tumor tissues." (PMID 33849528, 2021). "Previously we had established that mice deficient in myeloid differentiation primary response gene 88 (MyD88, Myd88−/−) rapidly progressed to neoplasia when infected with H. felis." (PMID 33477306, 2021). "All results with different innate immune pathways suggest that MyD88 is essential for BCG-tumor treatment depending on a synergistic effect involving several MyD88-dependent TLRs working simultaneously and/or a TLR-independent effect." (PMID 34341449, 2021). "It was first shown that TLR2/TLR4- MyD88-mediated signaling was required for the optimal function of MDSCs and suppression of anti-tumor immunity in models of colon cancer and fibrosarcoma, suggesting an involvement of canonical NF-κB activation." (PMID 33572260, 2021). "Meanwhile, IL-10, TGF-β, TLR4, MYD88 and NF-κB in tumor tissue were increased, indicating that the LC model of mouse was successfully developed." (PMID 33967748, 2021). "Functional TLR4, and the adaptor MyD88, are required for dendritic cells to cross-present antigens from the dying tumour cells and activate tumour-specific T-cell immune response." (PMID 34771442, 2021). "In this study, we found that PcrV directly interacts with TLR4 expressed on macrophages, which induces TAM M1 polarization and enhances TAM-mediated killing of tumor cells via the TLR4/MyD88 signaling pathway." (PMID 34900687, 2021). "For example, MyD88 and IL-1β have protumor activities at an early stage and antitumor activities at a later stage in mouse tumor models." (PMID 33946044, 2021). "These high-risk genes were also associated with the gene expression of M2-like tumor-associated macrophages (CD163), and MYD88 expression." (PMID 34945004, 2021). "TLR4 activation can boost immune system defense against tumor cells through MyD88 which leads to activation or maturation of immune cells such as dendritic cells (DCs), macrophages and T cells." (PMID 34844644, 2021). "The results suggest that there is a synergistic effect of several receptors that signal via the MyD88-dependent pathway favoring the action of BCG in tumor treatment." (PMID 34341449, 2021). "The importance of the IL-33/ST2/MyD88 axis for tumor inhibition was further confirmed in the CD8+ T cells-mediated tumor immunity through mDCs in a mouse model of Lewis lung carcinoma." (PMID 34209038, 2021). "Overall, our results suggest the essential role of MyD88 to generate an efficient BCG anti-tumor response." (PMID 34341449, 2021). "The removal of the adaptor molecule MyD88 completely eliminated the effect of BCG in tumor volume reduction." (PMID 34341449, 2021).
tumor (continued). "CD8α:MyD88-expressing T cells improved antitumor responses in mice and was associated with TME alterations including generation of a unique tumor cytokine/chemokine signature, improved T-cell infiltration with reduced markers of T-cell exhaustion." (PMID 34344725, 2021). "Further, MyD88 has been reported to be overexpressed in GC compared with the adjacent non-tumor tissues and its overexpression was correlated with tumor, node, metastasis (TNM) stage and lymph node metastasis." (PMID 34440074, 2021). "MyD88 was the only molecule relevant for tumor regression after BCG treatment in vivo and also involved in activation of macrophages in co-culture with infected MB49." (PMID 34341449, 2021). "In ovarian cancer, TLR4 activation resulted in MyD88-dependent nuclear localization of NFκB, upregulating the production of IL-6 as well as the chemokines MCP-1 and GRO-α, which are all associated with tumor progression." (PMID 34572948, 2021). "As an example, an immunomodulatory molecule that inhibits TLR signaling (IMO-8400) has been demonstrated to affect tumor growth in MYD88 mutant cell line models." (PMID 33050534, 2020). "Our results provide evidences about the contribution of MyD88 in the regulation of inflammation, carcinogenesis, and tumor differentiation in gastric cardia tissue." (PMID 32477927, 2020). "A reduction in the incidence, size, and number of neoplasms induced by chemicals has been observed in TLR4- and MyD88-deficient mice, thus underscoring a supportive role of TLR signaling in hepatocarcinogenesis." (PMID 32012718, 2020). "On tumor research, one study found that activation of the TLRs-MyD88-NF-κB signaling pathway is necessary for Breg cells differentiation and the induced Breg cells with immunoregulatory functions can contribute to the suppression of anti-tumor immunity." (PMID 32973780, 2020). "The result showed that transfection of MYD88 siRNA significantly reduced tumor sphere formation from GBM cells infected with ADV." (PMID 32843056, 2020). "Further experiments suggested the IL-1α/IL-1R/MYD88/IL-6 pathway as responsible for the reduced anti-tumor efficacy of erlotinib and other EGFR inhibitors." (PMID 33115415, 2020). "In summary, our findings demonstrate that a periodontal pathogen (T. denticola)-rich environment profoundly influences the tumor microenvironment by enhancing TLR/MyD88 and integrin/FAK crosstalk and signaling pathways." (PMID 33002094, 2020). "In another study, inoculation of IL-33-expressing EL4, CT26 or B16.F10 tumor cells induced MyD88-dependent intratumoral expansion of ILC2 in mice that were indispensable for IL-33-mediated antitumor activity independently of eosinophils." (PMID 33329534, 2020). "Our bioinformatics study and published reports demonstrated that the TLR4/MyD88 signalling pathway plays a vital role in tumour suppression (Kang, Su, Sun, & Zhang, 2018; Murad, 2014)." (PMID 32144747, 2020). "Hypo EGFR TKI can induce hypoptosis in tumor cells, releasing tumor-derived danger-associated molecular patterns (DAMPs), that can activate cGAS-STING and Toll-like receptors (TLR)-Myd88, that are essential for type I interferon production." (PMID 32516941, 2020). "This study also demonstrated that XBP1 is activated by toll-like receptor (TLR) and myeloid differentiation primary response gene 88 (MyD88) signaling in tumor-bearing mice." (PMID 32635462, 2020). "Subsequently, an inflammatory microenvironment is generated via MyD88-dependent and independent pathways, promoting tumor development." (PMID 30636642, 2019). "MyD88 expression was significantly higher in tumor compared to adjacent non-tumor tissues in this model; this is similar to what has been observed in human HCC." (PMID 31303442, 2019). "This activated the innate immune response and induced a type I IFN signature in TLR4/MyD88-dependent manner, which stimulated antitumor T cell adaptive immunity and restrained tumor growth." (PMID 31324798, 2019).
tumor (continued). "MyD88 deficiency completely abolished the IFNβ production when co-culture β-lap-treated tumor cells with BMDCs from Myd88−/− mice." (PMID 31324798, 2019). "This study builds upon our previous observations and demonstrates the importance of TLR2 and MyD88 in MIP-mediated tumor regression." (PMID 31590685, 2019). "β-Lapachone-induced high mobility group box 1 (HMGB1) release activates the host TLR4/MyD88/type I interferon pathway and Batf3 dendritic cell-dependent cross-priming to bridge innate and adaptive immune responses against the tumor." (PMID 31324798, 2019). "HMGB1 binds with TLR, activating myeloid differentiation primary response gene 88 (MyD88), and finally activates NF-kB, which promotes the proliferation, invasion, and metastasis of tumor cells." (PMID 30962261, 2019). "MyD88 mRNA knockdown in tumor (∼70%) was slightly greater with the GalNAc-MyD88 ASO compared to the unconjugated compound." (PMID 31303442, 2019). "Further, recent studies have shown that TLRs are expressed in a variety of tumor cells through the MyD88 pathway to ultimately activate NFκB, stimulating stem cell associated factors and pathways, especially c-Myc within Wnt and Notch signaling." (PMID 30736860, 2019). "In the present manuscript, we have explored the role of MyD88–TLR signaling axis in the antitumor efficacy of MIP using mouse tumor model." (PMID 31590685, 2019). "Consistent with mRNA, MyD88 protein levels were also notably reduced by both MyD88 ASOs in tumor and more profoundly in adjacent non-tumor tissues, especially with the GalNAc-conjugated ASO when assessed by IHC (top)." (PMID 31303442, 2019). "Evidence for apoptosis was observed in tumor cells of the MyD88-ASO groups by IHC for active caspase-3." (PMID 31303442, 2019). "In this study, the NGS technique using molecular barcoding technology successfully detected the MYD88 L265P carried by minimal tumor cells included in unselected PBMCs at a sensitivity of 0.02%." (PMID 31483817, 2019). "Tumors (Cd4, tendency in Myd88, p = 0.07) and tumor resection (Myd88, Cd4, Tlr9, Cd38) eliminated these time-of-day differences by reducing light-phase gene expression relative to controls and or increasing dark phase expression." (PMID 31019214, 2019). "OC stem cell populations defined by CD44+ and Myeloid differentiation primary response 88 (Myd-88) expression have demonstrated self-renewal, chemoresistance and tumor-initiating properties and constitutive NF-κB activity." (PMID 31443240, 2019). "To demonstrate the presence of MyD88 in a cell population consisting exclusively of cardiomyocytes, we evaluated HL-1 cells, an atrial cardiomyocyte tumor line derived from C57BL/6 mice." (PMID 30067739, 2018). "On the contrary, CD8+ T cell-priming, NK cell activation, and potent antitumor activity in a prophylactic tumor challenge model in vivo were MyD88-dependent, suggesting a more downstream role of MyD88." (PMID 30619259, 2018). "Mechanistically, LATS1/2‐null tumour cells secrete nucleic acid‐rich extracellular vesicles, which induce a type I interferon response via the Toll‐like receptor MYD88/TRIF pathway, thus improving tumour immunogenicity." (PMID 28782275, 2018). "TLR signaling inhibitors have been shown to have an effect on tumor growth in MYD88 mutant cell line models and patient-derived DLBCL tumor xenograft mouse models." (PMID 30301877, 2018). "In regard to the detection sensitivity of MYD88 L265P mutation, it has been previously reported that although lower BM burden (<10% infiltrate) in patients could result to false negative results, AS-PCR is sensitive enough to detect the L265P mutation in tumor cells as low as 1.25%." (PMID 30026568, 2018). "We found that the xenografts produced from Lnc-Myd88-overexpressed cells grown faster than the controls, and the final tumor volume and weight were larger than the controls." (PMID 29022910, 2017).